PKD1 (polycystin 1, transient receptor potential channel interacting)
Diseases named in the same sentence as PKD1 in open-access papers (continued):
Sharing a sentence is not in itself a finding about the gene and the disease.
tumor (continued). "Thus, PKD1 appears to play a distinct role in tumor angiogenesis compared to physiological angiogenesis." (PMID 23874489, 2013). "Interestingly, tumor angiogenesis was completely abolished in PKD1 morphants using the zebrafish/tumor xenograft angiogenesis assay." (PMID 23874489, 2013). "Cells reexpressing PKD1 formed not only less but also much smaller tumor colonies in the lungs." (PMID 23971832, 2013). "When we analyzed tumor edges and connections to the mouse mammary tissue in control cells, we observed a reduced local invasion in the tumors treated with decitabine and reexpressing PKD1." (PMID 23971832, 2013). "However, the inhibitory effects of decitabine on tumor cell invasion were partially restored in PKD1-knockdown cells." (PMID 23971832, 2013). "Taken together, there is compelling evidence that PKD1 could repress cell proliferation in certain tumor types, although the underlying molecular mechanisms are not fully understood." (PMID 33807058, 2021). "In addition, we demonstrate that PKD1 inhibition reduces tumor growth in vivo in a TNBC PDX model." (PMID 29796183, 2018). "Thus, overexpression of PKD1 promoted the growth of HNSCC tumor xenografts." (PMID 30419840, 2018). "Additionally, analysis of the mRNA expression data from the TCGA cohort via cBioPortal demonstrated low mRNA expression in most tumor tissues, and PKD1 mRNA was downregulated in 87% HNSCC tumors (459 out of 530 cases with over 2-fold mRNA downregulation), which is consistent with our findings." (PMID 30419840, 2018). "Furthermore, the increase of the G-protein coupled receptor LPA1 in the tumor endothelium may render TAECs more sensitive to DIO-derived LPA, thereby leading to sustained nuclear PKD-1 signaling for de novo tumor arteriogenesis." (PMID 28186980, 2017). "Therefore, PKD1 could be a promising new target to prevent precancerous lesions and tumor formation, but also progression of tumors." (PMID 27649783, 2016). "The most well-characterized isoform is PKD1, which is involved in several physiological processes, such as oxidative stress response, cell motility and also in several pathological processes, such as cardiac hypertrophy, tumor development and tumor angiogenesis." (PMID 25874616, 2015). "Although loss of PKD1 does not differentially affect the response of organoids or tumors to cytotoxic regimens, the lower baseline of tumors in Apc−/−Pkd1−/− mice results in a more effective reduction in total tumor burden following treatment with these agents." (PMID 37542051, 2023). "PKD1 overexpression also promoted GPCR agonists bombesin and gastrin-releasing peptide-induced ERK1/2 activity and potentiated bombesin-stimulated tumor cell proliferation in head and neck squamous cell carcinoma." (PMID 33807058, 2021). "The authors showed that PKD1 phosphorylated MTA1 and triggered polyubiquitination and proteasomal degradation of MTA1, therefore inhibiting tumor cell migration and invasion." (PMID 33807058, 2021). "We found that a subset of CD44+ BCSCs with high expression levels of PKD-1 and CD36 were localized within or near blood vessels and tumor nests." (PMID 34168243, 2021). "Since IHC were performed on serial sections, in order to demonstrate that presence of PKD1 and phosphorylation of PIP5K1C at S448 occur in the same tumor cells, we performed co-immunofluorescence analyses on our tissues." (PMID 30555634, 2018). "As for the PKD1 isoform, we found a tendency of elevated expression with tumor progression, but the differences were not significant (p = 0.051)." (PMID 39408603, 2024).
tumor (continued). "A similar expression pattern is also observed in other tumor types: in colorectal cancer (CRC), PKD1 is expressed only in normal colon cells, PKD2 is the dominant isoform at the transcriptional level in tumor samples, and both PKD2 and PKD3 are highly expressed in CRC cell lines." (PMID 37293129, 2023). "As shown in a log fraction nonresponding figure, there was a significant decrease of tumor formation efficiency (TFE) in PKD1-knockdown BON cells." (PMID 36497140, 2022). "Inhibition of the PKD1 pathway may facilitate the elimination of specific CSC subsets, thereby curbing tumor progression and metastasis." (PMID 36497140, 2022). "The elevation of PKD1 and CD44 was particularly high in tumor cells close to the blood vessels." (PMID 36497140, 2022). "To further validate PKD1 signaling in the maintenance CSC traits in pNETs, we performed a well-established, and most widely accepted, in vitro limiting dilution tumor assay to assess the impact of this molecule in the regulation of tumor-initiating potential, a key functional feature in CSCs." (PMID 36497140, 2022). "BPA also significantly increased the mean tumor volume, regardless of the cells injected, but more importantly when cells overexpress PKD1." (PMID 32082170, 2019). "In the presence of BPA, tumor volumes were significantly higher, 45.67 ± 20.74 mm3 and 10.59 ± 3.20 mm3 after 60 days, for cells overexpressing or not PKD1, respectively." (PMID 32082170, 2019). "Importantly, under in vivo condition or in the presence of an activating mitogen such as GRP or bombesin, PKD1 and PKD2 act to promote tumor cell proliferation." (PMID 30419840, 2018). "Our data revealed that the expression of PKD1 was significantly lower in localized HNSCC tumors and metastases, a finding that was further confirmed in patient-paired tumor tissues where PKD1 was downregulated at both mRNA and protein levels in tumors as compared to the normal mucosa." (PMID 30419840, 2018). "Since we had shown that PKD-1 was involved in downstream signaling of the LPA pathway in MVECs, we examined the phosphorylation status of endothelial PKD-1, a downstream signaling of LPA pathway in the tumor endothelium." (PMID 28186980, 2017). "Analyses of human samples of PDA indicated strong correlation between PKD1 expression and presence of p65 in tumors, but no expression of both proteins in “normal” acinar tissue, adjacent to the tumor." (PMID 27649783, 2016). "Two genes (PKD1 and PKD2) coding for transient receptor potential polycystic (TRPP), a family of transient receptor potential (TRP) ion channels, were down-regulated in tumor tissues." (PMID 24466154, 2014). "In Matrigel Transwell assays, the induction of constitutively-active PKD1 inhibited tumour cell invasion in a similar way shown for cells transiently-transfected with active PKD1 (data not shown)." (PMID 19243594, 2009). "Interestingly, the individual BC cells with positive co-staining for both PKD-1 and CD44 were located outside of the tumor nest in patient BC specimens, suggesting that PKD-1 signaling may promote metastatic potential via maintenance of CSC phenotype." (PMID 34168243, 2021). "Indeed, tumor volumes of BPA-free mice injected with MCF-7 cells overexpressing or not PKD1 were 1.44 ± 0.05 mm3 and 4.09 ± 2.89 mm3 after 60 days, respectively." (PMID 32082170, 2019). "Although the difference in the growth profiles of the tumor xenografts were not statistically significant (p > 0.05), the PKD1-c1 clone displayed a trend of faster growth rate, as reflected in the median tumor volume over time, as compared to the control Con-c9." (PMID 30419840, 2018). "Interestingly, LPA/PKD-1 signaling suppresses CD36 transcription and reprograms MVECs for arteriogenic gene expression via a nuclear HDAC7-FoxO1 complex, implicating microvascular remodeling and tumor arteriogenesis." (PMID 27200349, 2016).
tumor (continued). "Finally, we showed that PKD1 expression does not correlate with classical clinical and pathological prognostic factors (SBR histological grade, macroscopic tumour size, PR and ERBB2 statuses and PIK3CA mutation status)." (PMID 25287328, 2014). "As compared to established inhibitors of tumor angiogenesis like Bevacizumab, PKD1 represents a more specific therapeutic target anticipating less side effects than generally blocking VEGF since physiological angiogenesis is only slightly impaired by silencing of PKD1." (PMID 23874489, 2013). "We found that MMP9 expression was significantly reduced only in the decitabine-treated control tumors (scrambled control shRNA, or scr-shRNA), but not in tumors generated with PKD1 shRNA cells or in saline-treated tumors, in which local tumor cell invasion was observed." (PMID 23971832, 2013). "However, given the plethora of signaling modules that drive angiogenesis, the precise role of PKD1 in both physiological and tumor angiogenesis in vivo has not been worked out so far." (PMID 23874489, 2013). "However, as previously discussed by Eiseler and colleagues, this does not change the fact that PKD1 may well play a significant role in tumor growth, possibly during tumor formation, either in the early stages of disease or after metastasis." (PMID 37293129, 2023). "However, in our tumor samples, PKD1 protein was not expressed, or expressed at low levels." (PMID 33138224, 2020). "By identifying PKD1 as a functional non-genomic target of BPA both in vivo and in vitro, we provide an important step forward in understanding the molecular mechanisms involved in tumor development regulated by this endocrine disruptor." (PMID 32082170, 2019). "However, interestingly, induction of PKD1 in vivo by Dox provided a slight growth advantage to the HNSCC tumor xenografts and resulted in a significant increase in final tumor weight in Dox-induced vs the non-induced tumors." (PMID 30419840, 2018). "The fact that leukocyte infiltration patterns are altered and reduced by absence of Pkd1, both in lesions and following treatment with DSS, may in part be influenced indirectly by changes in the tumor microenvironment—a topic of considerable interest for future investigations." (PMID 37542051, 2023).
genetic disease (23 papers, 2007 to 2025). "The TSC2/PKD1contiguous gene syndrome is a rare genetic disorder caused by a large deletion on chromosome 16p13.3 that simultaneously affects theTSC2 and PKD1 genes." (PMID 40822828, 2025). "ADPKD is a hereditary disease with complex phenotype and genetic heterogeneity, and most are caused by variants of the PKD1(16p13.3, 78%) or PKD2 (4p21, 15%) gene." (PMID 37953234, 2023). "Other than the genes identified as mutant in PKD (Pkd1 [the wild-type of which induces p21 ] and Pkd2), there is a striking paucity of gene targets in this common genetic disease." (PMID 17714589, 2007). "ADPKD is a genetic disease suspected to be caused by mutations in PKD148 that are reported to lead to a lack of functional PKD1—eventually manifesting in dose-dependent cystogenesis." (PMID 41094040, 2025). "A rare genetic disorder, known as TSC-2/PKD-1 contiguous gene syndrome, occurs when a large deletion on chromosome 16 affects boththe TSC2 and PKD1 genes." (PMID 40822828, 2025).
infection (9 papers, 2013 to 2025). The state of being infected such as from the introduction of a foreign agent such as serum, vaccine, antigenic substance or organism. "Our findings revealed that the levels of Gata2, Fat4 and Pkd1, which are related to cell polarization, as well as Egfl7, Nrp1 and Foxc2, which are related to valve development, were downregulated after infection." (PMID 38638427, 2024). "Infection with Adv-PKD1 and Adv-PKD3 reversed the anti-proliferative effects of 1-NA-PP1." (PMID 24086585, 2013). "We found that both mRNA and protein levels of PKD1(Prkd1), PKD2 (Prkd2), and PKD3 (Prkd3) were increased after HCoV-229E or HCoV-OC43 infection." (PMID 39540754, 2024). "Additionally, genes involved in calcium signaling and ion channel regulation—PKD1, PKHD1, TRPC1, TRPM6, and TRPM7—highlight the importance of cellular homeostasis and signaling during infection." (PMID 41114509, 2025). "Notably, PKD3 expression was observed to be in contrast to PKD1 and PKD2 from the early to late stages of infection, indicating the potential for different PKD family proteins to play distinct roles in the replication cycle." (PMID 39540754, 2024). "Compared with those found in neurons without infection with shRNA, the knockdown of PKD1 did not produce any change in the internalization of NMDARs induced by treatment with DHPG or with high NMDA/glycine." (PMID 26584860, 2015). "As demonstrated with Western Blots using phospho-specific antibodies infection with N927 but not with N138 activated PKD1." (PMID 23717204, 2013). "We found that infection with PKD1 shRNA (Open Biosystems/Thermo Fisher Scientific, Lafayette, CO) selectively reduced the expression of endogenous PKD1 without affecting the expression of other proteins such as PKC-α when compared with those following infection with control shRNA." (PMID 26584860, 2015). "Moreover, inhibiting PKD1 by the application of a protein kinase inhibitor such as Staurosporine, or by the knockdown of PKD1 through infection of PKD1 shRNA does not affect the regulated NMDAR endocytosis but prevent NMDAR endocytosis-induced phosphorylation and inhibition of remaining NMDARs." (PMID 29614089, 2018). "However, PKD1 shRNA infection prevented the increases in the serine phosphorylation of both the GluN2A and GluN2B subunits whereas infection of control shRNA did not alter the increases in the serine phosphorylation induced by DHPG or high NMDA/glycine treatment." (PMID 26584860, 2015). "Consistently, we did not observe additional density corresponding to PKD1 in the AAV1-AAVR complex, suggesting that PKD1 may affect AAV1 infection via another mechanism rather than through direct interaction with the virus." (PMID 31434885, 2019).
kidney (7 papers, 2014 to 2023). "To elucidate the mechanisms underlying the genetic interaction between Pkhd1 and Pkd1 in kidney cystogenesis, we examined whether the loss of FPC alters the expression and cleavage of PC1." (PMID 37845212, 2023). "To assess the potential of DST-PCR to detect homozygous indel mutations, we attempted to induce DSB in exon 11 of endogenous murine polycystic kidney disease 1 gene (Pkd1) after CRISPR/Cas9 gene editing using Pkd1 sgRNA in mIMCD-3 cells." (PMID 35804017, 2022). "Similar changes were confirmed in cystic kidney tissue from a Pkd1 mouse model, excluding the possibility of secondary changes in late-stage or end-stage disease in human tissues." (PMID 32663194, 2020). "Exocrine pancreas degeneration has also been described in several mouse models with ciliary defects including Ift88 and Pkd1." (PMID 28410364, 2017). "Our study found PKD1 mRNA levels to be higher in lung NETs than in lung NECs." (PMID 33138224, 2020).
cardiovascular disease (4 papers, 2016 to 2025). "Besides, PKD1-deficient mice are susceptible to cardiac dysfunction, thus highlighting the significance of PKD1 in regard to cardiovascular disease." (PMID 31757932, 2019).
autosomal dominant disease (3 papers, 2018 to 2026). Autosomal dominant form of disease. "In contrast to most ADPKD mouse models, which utilize Pkd1-/- null mutants, we explore these mechanisms using a Pkd1 heterozygous genetic model, which could more accurately reflect the aberrant epigenetic regulatory mechanisms that facilitate progression of autosomal dominant disease in humans." (PMID 37305656, 2023).
head and neck tumor (1 paper, 2018). "PKD1 expression was further analyzed by immunohistochemistry in a total of 124 sporadic head and neck tumor tissues and 74 normal tissue specimens, among which 56 were normal tissues adjacent to the tumors (sporadic)." (PMID 30419840, 2018).
metabolic disease (1 paper, 2022). A congenital disorder (due to inherited enzyme abnormality) or acquired (due to failure of a metabolically important organ) disorder resulting from an abnormal metabolic process. "As an additional link between kidney inflammation and metabolic disease, LKB1 forms a complex with PC1 to suppress the expression of MCP-1 in tubular epithelia; the tubular deletion of Lkb1 or Pkd1 restores MCP-1 expression and causes monocyte/CCR2+ macrophage recruitment." (PMID 36106024, 2022).
neurological diseases (1 paper, 2022). "Particularly, defects in synapse formation and function lead to various neurological diseases, and a recent study suggests that protein PKD1 functions upstream of N-cadherin, a classical synaptic adhesion molecule, to promote functional synapse formation." (PMID 35559026, 2022).
skeletal diseases (1 paper, 2026). "This suggests that the Kif3a mutation may play a compensatory role in a Pkd1-deficient background, thereby alleviating skeletal diseases caused by Pkd1 deletion by inhibiting the differentiation of BMSCs into adipocytes." (PMID 41602825, 2026).
vasculopathy (1 paper, 2023). "Specifically, all four patients with structural vasculopathy subtype had a monogenic etiology (4/4, 100%): KRIT1 for CCM, RNF213 for MD, ENG for HHT, and PKD1 for PKD." (PMID 36580209, 2023).
PKD1 also shares sentences with these, for which no sentence is quoted: renal failure (16 papers); liver disease (6); triple-negative breast carcinoma (4); cardiomyopathy (3); genetic renal disease (3); heart failure (3); adenocarcinoma (2); congenital nephrotic syndrome (2); gastric tumors (2); nephronophthisis 15 (2); schizophrenia (2); urinary tract infection (2); anaemia (1); aortic root dilatation (1); autosomal dominant Alport syndrome (1); autosomal dominant polycystic liver disease (1); basal cell carcinoma (1); Benign familial hematuria (1); benign schwannoma (1); bilateral frontoparietal polymicrogyria (1); cardiac rhabdomyoma (1); cataract (1); cerebral cavernous malformation (1); Cerebral ischemia (1); chondrodysplasia (1); coarctation of aorta (1); colorectal tumors (1); communicating hydrocephalus (1); congenital anomalies of the kidney and urinary tract (1); connective tissue disorder (1).
A further 76 diseases each share a sentence with PKD1 in 1 paper.